LGALS7 (galectin 7)
Diseases named in the same sentence as LGALS7 in open-access papers (continued):
Sharing a sentence is not in itself a finding about the gene and the disease.
Gestational Diabetes Mellitus (1 paper, 2024). "Due to its properties and the known influence of galectin-7 in various processes, this study focusses on galectin-7 in gestational diabetes." (PMID 39337670, 2024). "Further studies are needed to show the correlation of galectin-7 and the development and maintenance of gestational diabetes mellitus." (PMID 39337670, 2024). "This study examines the expression of galectin-7 in the placentas of women with gestational diabetes (GDM), compares it to its expression in healthy pregnancies, and evaluates the associated clinical outcomes." (PMID 39337670, 2024). "In summary, current data regarding the variety of functions and involvements of galectins in inflammatory and metabolic processes qualifies galectin-7 as a candidate to investigate in gestational diabetes mellitus." (PMID 39337670, 2024).
hemorrhagic stroke (1 paper, 2022). A stroke caused by a bleed on the brain. "This is the first study to genotype the galectin-7 promoter in patients with hemorrhagic stroke." (PMID 35401111, 2022).
hypopharyngeal squamous cell carcinoma (1 paper, 2010). "In contrast, other reports have demonstrated that galectin-7 is up-regulated in other cancers such as hypopharyngeal squamous cell carcinoma." (PMID 20546628, 2010).
intracerebral hemorrhage (1 paper, 2022). A cerebrovascular disorder characterized by bleeding into one or both cerebral hemispheres including the basal ganglia and the cerebral cortex. "The goal of this study was to determine whether a significant relationship exists between human galectin-7 gene LGALS7 promoter region polymorphisms and the risk of stroke due to non-traumatic intracerebral hemorrhage (ICH)." (PMID 35401111, 2022).
inverted papilloma (1 paper, 2014). An endophytic benign papillary epithelial neoplasm that results from the invagination and proliferation of epithelial cells in the underlying stroma. "Indeed, epithelial overexpression of galectin-3 (P=0.0002), galectin-4 (P<10−6), galectin-7 (P<10−6) and galectin-9 (P<10−6) was observed in inverted papillomas compared to non-malignant diseases." (PMID 24859692, 2014).
laryngeal squamous cell carcinoma (1 paper, 2010). A squamous cell carcinoma that arises from the larynx. "For example, nuclear localization of galectin-7 was associated with the initiation of tumorigenesis in laryngeal squamous cell carcinomas." (PMID 20546628, 2010).
lung diseases (1 paper, 2026). "OBJECTIVE: Galectin-7, a β-galactoside-binding lectin involved in inflammation, immune regulation, and apoptosis, has been implicated in the development and progression of various lung diseases." (PMID 41761148, 2026).
non-small cell lung carcinoma (1 paper, 2024). A group of at least three distinct histological types of lung cancer, including non-small cell squamous cell carcinoma, adenocarcinoma, and large cell carcinoma. "In our study, we were able to show that galectin-7 could serve as a new prognostic biomarker and is also a potential new drug target in non-small cell lung cancer." (PMID 39465762, 2024).
obstetric disorder (1 paper, 2024). Disorder associated with pregnancy, childbirth, and puerperium. "A correlation between the expression of galectin-7 in cancer and GDM and obstetric disorders has not yet been described, and further studies on this are recommended." (PMID 39337670, 2024).
ovarian tumors (1 paper, 2026). "This study aimed to evaluate the usefulness of osteopontin and galectin-7 on the diagnosis of ovarian tumors." (PMID 41899101, 2026).
papilloma (1 paper, 2023). A benign epithelial neoplasm that projects above the surrounding epithelial surface and consists of villous or arborescent outgrowths of fibrovascular stroma. "Considerable differences were found between Tg46 and WT or Lgals7−/− animals in the total number of papillomas and particularly in lesions larger than 2 mm." (PMID 36693903, 2023). "On the contrary, Lgals7−/− mice showed delayed occurrence of skin lesions compared to WT and Tg46 animals, and consistently low or even decreasing number of papillomas per mouse." (PMID 36693903, 2023). "In vivo, carcinogen-treated Lgals7−/− animals adoptively transferred with Gal-7-conditioned monocytic myeloid cells developed higher number of papillomas, whereas depletion of these cells in Tg46-treated mice led to reduction in the number of tumors." (PMID 36693903, 2023). "Interestingly, constitutive expression of Gal-7 in KCs (Tg46 mice) resulted in a higher number of papillomas per mouse and an earlier appearance of tumors, compared to WT and Lgals7−/−animals." (PMID 36693903, 2023). "Notably, Lgals7−/− mice receiving M-MDSC-Gal-7, showed not only an earlier appearance of papillomas, but also an increased number of total papillomas, compared to those receiving M-MDSCs-C." (PMID 36693903, 2023).
preeclampsia (1 paper, 2016). Preeclampsia is a hypertensive disorder of pregnancy that is characterized by new-onset hypertension with proteinuria presenting after 20 weeks of gestation, and depending on mild or severe forms may initially present with severe headache, visual disturbances, and hyperreflexia. "Further results showed that serum galectin-7 was slightly elevated during the first trimester in women who developed preeclampsia later in pregnancy." (PMID 27136536, 2016).
rheumatoid arthritis (1 paper, 2021). A chronic, systemic autoimmune disorder characterized by inflammation in the synovial membranes and articular surfaces. "Anti-galectin-4 and -8 aAbs were found in SLE and rheumatoid arthritis (RA); anti-galectin-7 aAb in SLE; and anti-galectin-8 and -9 aAbs in SLE and RA." (PMID 35008499, 2021).
Stroke (1 paper, 2022). Sudden impairment of blood flow to a part of the brain due to occlusion or rupture of an artery to the brain. "Here, galectin-7 is assessed as a novel genetic risk factor associated with poor clinical ICH outcomes in patients with stroke of the Chinese Han population." (PMID 35401111, 2022). "In this study, we studied the entire genomic DNA sequence and neighboring sequences of LGALS7 genes of 24 patients with stroke and 70 healthy controls belonging to the Chinese Han population." (PMID 35401111, 2022). "Therefore, due to its tissue distribution, galectin-7 may be associated with stroke, although the association between galectin-7 and stroke risk has not been reported." (PMID 35401111, 2022).
T-cell lymphoma (1 paper, 2023). "High expression of levels galectin-7 promote its metastasis in T-cell lymphoma and play a role in sensitizing chemotherapy in urothelial cell carcinoma." (PMID 37762693, 2023).
thymoma (1 paper, 2016). A neoplasm arising from the epithelial cells of the thymus. "Protein s100-a10 and galectin 7 were only present in A and B3 thymomas respectively when matched with normal thymus tissue." (PMID 27832160, 2016).
ulcer (1 paper, 2019). "Increased Myl9 and Lgals7 levels might demonstrate a tendency in the ulcer areas to progress to cancerous lesions." (PMID 31391093, 2019).
cancer (46 papers, 2007 to 2026). A tumor composed of atypical neoplastic, often pleomorphic cells that invade other tissues. "While its precise function appears to be cancer-type dependent, Galectin-7 is broadly implicated in regulating cell adhesion, apoptosis, proliferation, and immune modulation." (PMID 41306978, 2025). "Cancer cell 2 expressed Sprr1a, Lgals7, and Ifitm1, which are associated with the mesenchymal/basal-like subtype and a poor prognosis in PDAC." (PMID 37998349, 2023). "Galectin-7 has attracted significant attention as a diagnostic biomarker, tumor progression marker, and therapeutic target for cancer treatment." (PMID 33233689, 2020). "Other carcinomas are also associated with decreased galectin-7 expression such as stomach, urothelial and cervix cancer." (PMID 29257082, 2017). "Accordingly, several groups reported an association between galectin-7 expression levels and cancer aggressiveness as we will discuss in the following section." (PMID 29257082, 2017). "Etopic expression of galectin-7 in cancer cells increased their susceptibility to apoptosis and suppressed tumor growth." (PMID 23985992, 2013). "Targeting galectin-7 may represent a valuable strategy to overcome cancer-associated immunosuppression and the prevention of metastasis in EOC." (PMID 34827718, 2021). "Galectin-7 has been previously implicated in cell migration during re-epithelialization events after corneal or epidermal injury and in promoting invasiveness during cancer progression." (PMID 30774578, 2019). "Finally, we will address the association of galectin-7 with carcinoma and its putative function in cancer progression." (PMID 29257082, 2017). "A few reports document regulation of the LGALS7 gene, encoding galectin-7, in cancer." (PMID 28481247, 2017). "Galectin-7, a homodimer galectin, is implicated in various biological effects including cell proliferation, differentiation, apoptosis, collective cell migration and immune-modulatory, which plays a completely discrepant role in different types of cancers." (PMID 27259255, 2016). "In the context of cancer, LGALS7 has been shown to modulate tumor cell behavior, potentially promoting or inhibiting tumor growth and metastasis, depending on the tumor type and microenvironment." (PMID 40634299, 2025). "Galectin-7 (Gal-7) exhibits distinct, context-dependent roles in cancer biology, functioning either as a tumor suppressor or promoter depending on the tissue type and molecular context." (PMID 40710343, 2025). "That is the case for genes encoding for galectin-7 (LGALS7 and LGALS7B), highly expressed in SCC, that were found to be downregulated in cancer cells from cutaneous SCC but upregulated in the ones from esophagus SCC." (PMID 38384845, 2024). "This is a clear contrast with the expression of galectin-7 in breast cancer, where its expression not only correlates with cancer progression but also promotes metastasis." (PMID 37753083, 2023). "The expression of galectin-7 is also dependent on the subtype of cancer and the location of the disease inside the cell; it is absent in carcinomas of basal cells and present in squamous cell tumors, which are head and neck malignancies." (PMID 38202898, 2023).
cancer (continued). "The expression of galectin-7 varies between cancer types; it is expressed less in malignancies of the skin, cervix, and stomach and more in cancers of the gastrointestinal tract, breast, thyroid, larynx, and indolent lymphoproliferative diseases." (PMID 38202898, 2023). "Galectin-7 also reduces the invasiveness of prostate cancer cells by inhibiting cell motility and rendering cancer cells sensitive to apoptosis in response to chemotherapeutic agents." (PMID 36873388, 2023). "Galectin-7 is also involved in cell adhesion and migration and functions in wound healing, cancer progression, embryonic development, allergic inflammation, autoimmune diseases, and transplant rejection." (PMID 35677161, 2022). "For example, extracellular galectin-7 promotes cancer via binding to cell surface receptors of cancer cells and induce de novo transcriptional activation of LGALS7, which in turn render cells resistant to pro-apoptotic drugs." (PMID 34827718, 2021). "A galectin-7 knockdown in the cancer cells showed increased viability against paclitaxel-induced apoptosis." (PMID 34827718, 2021). "The ability of galectin-7 to augment MMP-9 expression in cancer cells has also been established using cancer cells transfected with eukaryotic expression vectors containing the gene encoding galectin-7 (i.e., LGALS7)." (PMID 34198494, 2021). "Increased expression of MMP-9 induced by galectin-7, which occurs at both the mRNA and protein levels, has in many cases been documented by adding recombinant human galectin-7 to cancer cells." (PMID 34198494, 2021). "It is believed that N-linked glycosylation of Tid1 is required to interact with galectin-7 to downregulate galectin-7, which in turn can attenuate cancer progression and metastasis." (PMID 34827718, 2021). "Nevertheless, our goal for this section is to provide the reader with a brief overview of the presence and roles of galectin-7 in most cancers/cancer types by covering mostly recent publications." (PMID 34827718, 2021). "There are a number of papers published regarding the subject of cancer (development) and the roles of (targeting) galectins, and even galectin-7 in particular." (PMID 34827718, 2021). "A weaker immunostaining of galectin-7 was also noticed in poorly versus highly differentiated tissues from patients with esophageal squamous cell carcinoma as well as in normal versus cancer tissues." (PMID 32731422, 2020). "On the contrary, squamous epithelial and mucous tumours from head and neck, oesophagus and thyroid cancer do express higher galectin-7 levels than normal tissues." (PMID 29257082, 2017). "Among these galectins, galectin-7, being expressed mostly in stratified epithelia, has been mainly studied in carcinomas and its implications in cancer were referenced only in a few tens of published articles." (PMID 29257082, 2017). "The function of galectin-7 in collective cell migration is relevant in pathological conditions such as cancer progression." (PMID 29257082, 2017). "As a consequence, galectin-7 appeared in the dedicated studies as a potential target for clinical approaches either as a prognostic marker, a direct modulating protein in cancer or a therapeutic target for inhibitors." (PMID 29257082, 2017). "Consistently, in OSCC cell lines, galectin-7 downregulation reduces cell migration and invasion whereas its overexpression enhances cell migration and invasion of cancer cells." (PMID 29257082, 2017). "Among these galectins, galectin-7 is abnormally expressed in various cancers, most prominently in carcinomas, and is involved in cancer progression and metastasis but its precise functions in tumour biology remain poorly understood." (PMID 29257082, 2017). "In this issue, we will focus on the physiological functions of galectin-7 in epithelia and present the alterations of galectin-7 expression in carcinomas with the aim to describe its possible functions in tumour progression." (PMID 29257082, 2017).
cancer (continued). "CSPP1 is a mitosis regulator; LGALS7 and PDE2A are overexpressed in different cancer types; LDHA encodes one of the major glycolysis enzymes." (PMID 27359056, 2016). "To further examine whether we could find an association between C/EBPβ and galectin-7 expression profiles in epithelial tissues, we looked at the Human Protein Atlas database, which contains high-resolution images showing the spatial distribution of proteins in normal and cancer tissues." (PMID 24789216, 2014). "It is also supported by data found in public databases, which showed that C/EBPβ and galectin-7 have an almost identical distribution pattern in both normal and cancer tissues." (PMID 24789216, 2014). "Although regulation of the galactoside-binding lectin galectin-7 in cancer has been studied, its role in tumor formation and progression remains controversial." (PMID 23985992, 2013). "In contrast, stimulatory roles of galectin-7 in cancer development have also been widely demonstrated." (PMID 23985992, 2013). "Galectin-7 reportedly has some effects that oppose those of galectin-1: whereas galectin-1 promotes tumor growth and induces resistance to apoptosis, galectin-7 induces apoptosis in several types of cancer cells." (PMID 23530091, 2013). "Human galectin-7 (hGal-7), in particular, has been highlighted as an important marker in many types of cancer by either inhibiting or promoting tumour growth." (PMID 22059385, 2012). "LGALS7 plays a crucial role in immune cell function, inflammation, cell adhesion, migration, proliferation, and apoptosis; It has been implicated in the development and progression of various diseases, including CRC and other cancers." (PMID 40634299, 2025). "The presence of galectin-7 in cancer types has been investigated." (PMID 39337670, 2024). "Galectin-7 has a tumor-promoting function in diverse cancer types, including HNSCC25–27, therefore, it is plausible that the aggressive feature of CC1 might be associated with the expression of p-EMT and LGALS7B." (PMID 36828832, 2023). "Indeed, galectin-7 (expressed in CC1) promotes metastasis in various cancer types, including HNSCC30." (PMID 36828832, 2023). "Furthermore, an increase in galectin-7 expression has been shown to result in tumour progression through increased cancer cell invasiveness and a proapoptotic effect on immune cells." (PMID 37238197, 2023). "A better understanding of these relationships will help to develop a working hypothesis and model that will provide the basis for further research in the hope of establishing a new paradigm for tackling the role of galectin-7 in cancer." (PMID 34198494, 2021). "Such an association between galectin-7 and MMP-9 has been observed in many cancer types." (PMID 34198494, 2021). "Several studies have indeed shown that galectin-7 is associated with aggressive behavior of cancer cells and induces expression of MMP-9, a member of the matrix metalloproteinases (MMP) family known to confer invasive behavior to cancer cells." (PMID 34198494, 2021).